SP140L (SP140 like nuclear body protein)
Tractability: PROTAC: UniProt records ubiquitination sites on it; ubiquitination databases record sites on it; its protein half-life has been measured.
Target class: Epigenetic regulator; Bromodomain; Reader
Gene: Protein-coding gene on chromosome 2 (230,326,762 to 230,403,735, forward strand). Ensembl gene ENSG00000185404.
Subcellular location (Human Protein Atlas): Nucleoplasm
Gene Ontology:
Molecular function: DNA-binding transcription factor activity, RNA polymerase II-specific; DNA binding
Biological process: regulation of transcription by RNA polymerase II; defense response
Cellular component: nucleus
Genetic constraint (gnomAD): Loss-of-function variants: 55 observed, 61.08 expected, observed/expected ratio (o/e) 0.9, 90% interval 0.72 to 1.13. The upper end of that interval is the gene's LOEUF score, 1.13, which puts it in group 4 of 6, group 1 being the genes least tolerant of losing a copy. Missense variants: 534 observed, 522.02 expected, observed/expected ratio (o/e) 1.02, 90% interval 0.95 to 1.1. Synonymous variants: 206 observed, 184.96 expected, observed/expected ratio (o/e) 1.11, 90% interval 0.99 to 1.25.
Homologues: Orthologues: chimpanzee SP140L (98% identical), zebrafish ubtfl (10% identical), zebrafish ubtf (9% identical), tropical clawed frog ubtf (8% identical), Caenorhabditis elegans hmg-3 (7% identical), Caenorhabditis elegans hmg-4 (7% identical), Drosophila melanogaster Ssrp (7% identical), Drosophila melanogaster CG4617 (4% identical), Drosophila melanogaster HmgD (2% identical), Drosophila melanogaster HmgZ (2% identical). Paralogues in human: SP140 (77% identical), SP100 (58% identical), SP110 (37% identical), UBTF (10% identical), TOX3 (9% identical), TOX2 (9% identical), TOX4 (9% identical), TOX (8% identical), HMGXB4 (8% identical), SSRP1 (8% identical), SMARCE1 (7% identical), HMGB2 (7% identical), and 8 more.
Diseases named in the same sentence as SP140L in open-access papers:
SP140L is named in the same sentence as 12 diseases in open-access papers, as found by Europe PMC text mining. Sharing a sentence is not in itself a finding about the gene and the disease. The quoted sentences say what the papers report.
primary biliary cirrhosis (2 papers, 2015 to 2025). "Similarly to SP100 and SP140 protein, we detected serum autoantibodies to SP140L in patients with primary biliary cirrhosis using luciferase immunoprecipitation system and immunoblotting assays." (PMID 26347895, 2015). "In conclusion, our results show that SP140L is phylogenetically recent member of SP100 proteins and acts as an autoantigen in primary biliary cirrhosis patients." (PMID 26347895, 2015).
breast carcinoma (1 paper, 2025). "While SP100 acts as a tumor suppressor in malignancies like breast cancer, SP110 and SP140 are implicated in promoting oral squamous cell carcinoma and glioma progression, respectively, and SP140L is linked to poor prognosis in pancreatic adenocarcinoma." (PMID 41188771, 2025).
myositis (1 paper, 2025). "Luciferase immunoprecipitation system (LIPS) assays were performed to detect autoantibodies against full-length and protein fragments of SP140L and TIF1γ in serum samples from myositis patients, disease controls, and healthy controls." (PMID 40568657, 2025).
pancreatic adenocarcinoma (1 paper, 2025). "Further, SP140L member is likely related to the occurrence, development, and poor prognosis of pancreatic adenocarcinoma (PAAD)." (PMID 41188771, 2025).
systemic sclerosis (1 paper, 2025). A chronic disorder, possibly autoimmune, marked by excessive production of collagen which results in hardening and thickening of body tissues. "In contrast to the results seen with the full-length SP140L target antigen, only one anti-TIF1γ sample and one systemic sclerosis sample showed immunoreactivity, resulting in an overall specificity of 99%." (PMID 40568657, 2025).
tumor (4 papers, 2020 to 2025). "Here, we demonstrate a significant correlation between SP100, SP110, SP140, and SP140L genes’ expression and immune cell populations in the tumor microenvironment." (PMID 36614001, 2022). "We found a striking positive correlation between the SP subfamily of Bromodomain proteins, namely SP100, SP100, SP140, and SP140L, and the estimate score across all analyzed tumor types." (PMID 36614001, 2022). "Moreover, SP140L was found to be implicated in the PI3K/AKT and RAS/MAPK pathways, which are known to facilitate tumor cell growth and proliferation." (PMID 37354211, 2023). "While no studies exist directly in PAAD, SP140L’s ability to downregulate interferon-stimulated genes and viral DNA sensing in B cells reveals the possibility of downregulating tumor-associated macrophage phenotypic reprogramming and immune checkpoint expression." (PMID 41188771, 2025). "This systematic review underscores the dual oncogenic and tumor-suppressive roles of SP100 family proteins (SP100, SP110, SP140, SP140L) across 25 cancer types, shaped by context-dependent expression patterns, genetic/epigenetic alterations, and possible interactions with tumor microenvironments." (PMID 41188771, 2025).
cancer (3 papers, 2018 to 2025). A tumor composed of atypical neoplastic, often pleomorphic cells that invade other tissues. "After RAYYAN-assisted deduplication and screening, studies analyzing SP100, SP110, SP140, or SP140L alterations in human cancers (excluding cell lines studies) were included." (PMID 41188771, 2025). "This systematic review analyzed 29 studies (2004–2024) to evaluate the dual roles of SP100 family proteins (SP100, SP110, SP140, SP140L) across 25 cancer types." (PMID 41188771, 2025). "SP140L’s chromatin-binding elements and immune-specific activities make it a promising candidate for more studies on cancer development and metastasis, even though connections to EMT are still being explored." (PMID 41188771, 2025). "The Speckled Protein 100 (SP100) family, comprising SP100, SP110, SP140, and SP140L, has emerged as a critical player in cancer biology due to their roles in transcriptional regulation, chromatin modification, and immune signaling." (PMID 41188771, 2025). "As for CD274, only SP140L correlated negatively in five cancer types." (PMID 36614001, 2022). "Interestingly, except for miR-373-3p:circ-SP140L (both upregulated), other miRNA:circRNA pairs had opposing deregulated expressions: in the cancer samples, miRNAs were downregulated and their paired circRNAs were upregulated." (PMID 29682564, 2018). "The newest member of the SP100 protein family, SP140L, changes how accessible chromatin is and may be affecting the epithelial-mesenchymal transition (EMT), which is important for cancer development." (PMID 41188771, 2025).
SP140L also shares sentences with these, for which no sentence is quoted: autoimmune disease (1 paper); glioma (1); infection (1); oral squamous cell carcinoma (1); tendinitis (1).